RETN (resistin)
Diseases named in the same sentence as RETN in open-access papers (continued):
Sharing a sentence is not in itself a finding about the gene and the disease.
Obesity (continued). "Increases of leptin, resistin, and visfatin as well as decreases of adiponectin/leptin ratio accompany the expansion and/or the dysfunction of adipose tissue, and have been associated with a multitude of adverse obesity-related outcomes." (PMID 38159164, 2024). "In summary, our results provided the first evidence that the ECS and resistin are tightly associated, which could explain the key pathobiology of obesity, adipose tissue inflammation, mitochondria dysfunction, and insulin resistance." (PMID 39050819, 2024). "Increased white-adipose-tissue (WAT) content, which constitutes the hallmark of obesity, leads to enhanced secretion of adipokines, including leptin, resistin, interleukin 6 (IL-6), tumor necrosis factor-alpha (TNF-α), visfatin, vaspin, and retinol-binding protein 4 (RBP-4)." (PMID 38794651, 2024). "Furthermore, an imbalance among adiponectin (anti-inflammatory), leptin, and resistin contributes to the development of moderate inflammation associated with obesity and increased adipose tissue cell necrosis." (PMID 38495901, 2024). "Thus, similarly to other adipokines like leptin, resistin and IL-6 overproduced by the adipose tissue during obesity, MCP-1 plays a causal role in inflammation, insulin resistance and atherosclerosis during obesity." (PMID 38136564, 2023). "Preexisting obesity increases the concentration of leptin and resistin in the serum of pregnant women, which may be caused by the increased volume of adipose tissue." (PMID 37432262, 2023). "It has also been postulated that resistin is linked to obesity, insulin resistance, and diabetes." (PMID 37371984, 2023). "A human study revealed the association of resistin with obesity and impaired insulin sensitivity." (PMID 37371606, 2023). "Visceral adipose tissue is also resistant to insulin and leptin and is the site of altered secretion of molecules and hormones such as adiponectin, leptin, resistin, tumor necrosis factor and interleukin-6, which exacerbate cardiovascular disease associated with obesity." (PMID 37081416, 2023). "Contrary to ApN, resistin levels increase in obesity, and it has been proposed as a risk factor for dementia, as it counteracts the effects of insulin and promotes inflammation in obesity." (PMID 37732123, 2023). "Obesity and metabolic syndrome are associated with an elevated level of resistin." (PMID 36834693, 2023). "Major adipokines involved in the pathogenesis of obesity-related knee osteoarthritis include adiponectin, which appears to have a protective effect, as well as leptin, resistin and visfatin, which are associated with higher pain scores and more severe structural damage." (PMID 38275369, 2023). "However, prior to this, the comprehensive regulatory circuits of resistin with their precise direction of action in the association between obesity and IR in humans need to be defined." (PMID 37239098, 2023). "The authors of the study concluded that high levels of resistin in saliva, which are associated with obesity, may be one of the factors predisposing obese individuals to type 2 diabetes." (PMID 36835557, 2023). "It is also postulated that resistin is linked to obesity, insulin resistance, and diabetes." (PMID 35806278, 2022). "Additionally, hormonal mechanisms underlying the anti-obesity effect of chitoglucan were elucidated through the analysis of serum levels of leptin and resistin." (PMID 36612600, 2022). "The study suggested that its presence at such high expression levels may indicate that insulin resistant type 2 diabetes and obesity, strongly linked with resistin, may play a crucial role in determining breast cancer development in AA women." (PMID 36077676, 2022). "In addition to insulin, a recent finding suggested the role of the resistin hormone in an association between obesity and type 2 diabetes, and it represents a potential candidate for the etiology of insulin resistance." (PMID 36135388, 2022).
Obesity (continued). "Circulating resistin levels are elevated in mouse models of diet-induced and genetic obesity, suggesting that elevated resistin levels may be closely related to obesity and associated metabolic dysfunctions." (PMID 35909571, 2022). "Given its role in insulin resistance and inflammation, resistin could mediate inflammation in obesity and explain the relationship between obesity and associated metabolic diseases." (PMID 35909571, 2022). "Currently, leptin, resistin, and visfatin are the most widely used pro-inflammatory adipokines in experimental studies, as well as in clinical trials of anti-diabetic preparations and other therapeutics targeting obesity-associated diseases." (PMID 36499312, 2022). "This hormone is mainly secreted by white adipocytes; thus, the effect of resistin in obese patients may elucidate how obesity predisposes to insulin resistance, as the levels of this hormone are elevated in obese patients." (PMID 36262532, 2022). "For instance, obesity induced by a high-fat diet or the mutation of the leptin gene or receptor is associated with increased circulating resistin concentrations, whereas resistin expression was downregulated in rodent models with diet-induced obesity and suppressed by free fatty acids." (PMID 34579022, 2021). "In addition, there is a growing appreciation of the importance of newer adipokines, such as resistin, visfatin, and apelin, in obesity-linked cancers." (PMID 33535537, 2021). "Moreover, recent evidence suggests that adipokines (such as leptin, adiponectin, and resistin) secreted in adipose mass are closely associated with insulin resistance, obesity, and an early inflammatory stage of NAFLD pathogenesis." (PMID 33758311, 2021). "Furthermore, resistin is found to be associated with obesity, visceral fat, inflammation and IR and it can be a potential risk factor of MetS and comorbidities of CVD." (PMID 34209146, 2021). "Notably, other adipokine disorders caused by obesity, including resistin, visfatin, and SFRP5, are also proved to be key orchestrators in BC oncogenesis and progression." (PMID 34350120, 2021). "Resistin is a pro-inflammatory adipokine associated with insuline resistance and obesity." (PMID 34858196, 2021). "In addition, a meta-analysis suggested that resistin is an independent biomarker for the risk of obesity-related cancers." (PMID 34659568, 2021). "RETN concentration is associated with obesity and insulin resistance." (PMID 33859244, 2021). "Thus, C-peptide, insulin, leptin, PAI, GIP, GLP-1, ghrelin, resistin, and visfatin are closely associated with carbohydrate and lipid metabolism and BMI in obese patients, which contributes to the formation of IR in obesity." (PMID 33959145, 2021). "Dysfunction of cytokines and hormones such as leptin, ghrelin, insulin, GLP-1, resistin, and visfatin has been implicated causally in the pathogenesis of obesity but also as a mediator between excess fat mass and insulin resistance, T2D, and cardiovascular disease." (PMID 34620218, 2021). "Thus, while resistin is an established adipokine and has been shown in some cases to be associated with adverse health conditions such as obesity and insulin resistance, a clear role for resistin is still under active investigation." (PMID 32158768, 2020). "In our previous studies of DNAJC27 in the context of obesity and T2D, we demonstrated a positive association between DNAJC27 and the common obesity biomarkers leptin and resistin, and also that DNAJC27 levels were elevated in PBMCs, plasma, and adipose tissue from individuals with obesity and T2D." (PMID 32733386, 2020). "However, results also showed moderate increases of resistin, associated with obesity and type 2 diabetes in islet-seeded biomaterial treated diabetic mice." (PMID 32152396, 2020). "Furthermore, high levels of resistin have been associated also with an increased risk of non-obesity-associated malignancies, such as gastric, colon, and lung cancers." (PMID 32660156, 2020).
Obesity (continued). "At the same time, obesity, diabetes, high carbohydrate and unsaturated fat diet and chronic alcohol consumption, but not smoking, were described as cardiovascular risk factors correlated with elevated human serum resistin levels." (PMID 31881807, 2019). "Recently, among adipokines (i.e., cytokines associated with chronic inflammatory state and obesity) such as leptin, adiponectin, and resistin, only the serum level of resistin was found to be related strongly to the severity of pain in the patients undergoing laparotomy." (PMID 31258474, 2019). "Although resistin has been conclusively linked to the development of obesity and insulin resistance in rodents, disagreement persists regarding the pathogenic role of resistin in human obesity." (PMID 30906281, 2019). "Association of adiponectin, leptin, and resistin with inflammatory markers and obesity in dementia." (PMID 31969813, 2019). "A decreased resistin concentration by knocking out the resistin encoding gene or blocking resistin by antibody could protect against obesity-associated hyperglycemia, which is mainly due to recovering the response of the liver to insulin." (PMID 29785210, 2018). "Resistin (RETN) is an adipokine that is associated with obesity, inflammation, and various cancers." (PMID 30406149, 2018). "We further identified resistin among the top modulated adipokines secreted by 3T3-L1 adipocytes under obesity-associated metabolic conditions, thus constituting a plausible soluble mediator in the link between obesity, metabolic complications and breast cancer." (PMID 30524378, 2018). "ER stress induced by resistin may play an important role in the pathogenesis of vascular dysfunction or vascular diseases associated with obesity or other metabolic disorders." (PMID 30416448, 2018). "Resistin is an adipokine that is associated with obesity, inflammation, and various cancers." (PMID 30406149, 2018). "In conclusion, our data show that DNAJC27 is elevated in obese and T2D individuals and was positively associated with obesity biomarkers such as leptin and resistin suggesting that this protein may play a role in the pathophysiology of these disorders." (PMID 30131766, 2018). "Therefore, an increase in adiponectin secretion and decrease in resistin secretion are considered to have a synergistically beneficial effect on inhibiting the progress of MS associated with obesity and diabetes." (PMID 30294680, 2018). "Thus, obesity-associated factors including leptin and resistin are crucial for cancer cell growth as well as for outcome of therapeutic response." (PMID 29568521, 2018). "Adiponectin–resistin (AR) index was proposed as an indicator of metabolic risk in obesity." (PMID 29213336, 2017). "In a further study, the resistin-adiponectin ratio (RA index) was strongly associated with β-cell function—assessed by OGTT-derived indices—in two NGT cohorts with different degrees of overweight/obesity." (PMID 28846711, 2017). "There are several studies about resistin levels and obesity-related cancer risk." (PMID 28404934, 2017). "We found that resistin and lipocalin-2/ngal, two adipokines involved in obesity-associated dysmetabolic state and inflammation, were similarly and inversely associated with TRAIL when this cytokine was detected within the first IV deciles of circulating levels." (PMID 29056829, 2017). "Therefore, a meta-analysis was performed to assess the association between blood resistin levels and obesity-related cancer risk." (PMID 27509174, 2016). "However, more studies are required to clarify the mechanistic role of resistin in the association between obesity and breast cancer." (PMID 26729407, 2016). "It seems plausible that resistin levels may be associated with the incidence of obesity-related cancer." (PMID 27509174, 2016). "It suggests that leptin is a better markerof fat mass value than resistin and may be considered an independent risk factor forcardiac disorders that is largely dependent on obesity." (PMID 27627223, 2016).
Obesity (continued). "Resistin, one such gene, is linked to inflammation, obesity, and breast cancer risk." (PMID 27314854, 2016). "Higher resistin levels were found to be associated with increased obesity-related cancer risk." (PMID 27509174, 2016). "In conclusion, this meta-analysis suggests circulating resistin levels may be higher in obesity-related cancer patients than in normal controls, and an independent biomarker of obesity-related cancer risk." (PMID 27509174, 2016). "In addition to the storage of lipids in the adipose tissue, adipocytokines like adiponectin, leptin, TNF, IL-6, resistin play an important role in tissue physiology and have been shown to be linked to obesity, insulin resistance and β-cell dysfunction." (PMID 28702225, 2015). "Although RBP-4 and resistin have been associated with obesity and insulin resistance, and may be altered in pregnancy, they do not appear to be predictive of GDM development." (PMID 26110385, 2015). "The justification for thisphenomenon is that the increase of the release of free fatty acids, resistin, IL-6 andTNF-alpha by the adipose tissue and the reduction of the release of adiponectincontribute to the development of insulin resistance in obesity and increased risk ofdeveloping NAFLD6." (PMID 26734800, 2015). "Furthermore, we examined possible associations between serum resistin levels with obesity, insulin resistance and serum biochemical abnormalities related to GDM." (PMID 25945322, 2015). "On one hand, obesity-associated inflammation stimulates the adipocytes themselves to produce inflammatory mediators, on the other hand, these inflammation mediators aggravate inflammation and thus, increases resistin secretion and vice versa." (PMID 24559185, 2014). "Besides, the role of resistin in obesity-associated insulin resistance is yet controversial because additional evidence suggests that obesity and insulin resistance are related to decreased resistin expression." (PMID 25541889, 2014). "Finally, we also detected decreased levels of Resistin/RETN, an adipose-secreted hormone linked to obesity and insulin resistance in rodents." (PMID 24945157, 2014). "Therefore, this project evaluated the phenotypic relationship between obesity indices, resistin, adiponectin and cardiovascular risk markers in normoglycemic healthy individuals." (PMID 24353501, 2013). "However, to date there has been considerable inconsistent reports from the animal and clinical studies for or against the role for resistin as an important pathogenic factor in obesity, insulin resistance and type 2 diabetes." (PMID 23776497, 2013). "However, some recent genetic studies have demonstrated an association between resistin and insulin resistance and obesity." (PMID 23634778, 2013). "Resistin is an adipocytokine, associated with obesity and inflammation." (PMID 23497617, 2013). "Early reports suggested that resistin is associated with obesity and insulin resistance in rodents." (PMID 23497617, 2013). "Obesity is also recognized as the risk factor for stroke, because obesity is associated with hypertension and inflammation via secretion of adipokines, such as adiponectin, leptin, resistin, adipsin, plasminogen activator inhibitor-1, and inflammatory cytokines." (PMID 23431245, 2013). "Amplified resistin expression may indicate insulin-resistant type II diabetes and obesity are associated with AA breast cancer." (PMID 24324792, 2013). "However, the structure and biology of resistin differ substantially between species, and many aspects, specifically its association with obesity and its effects on insulin sensitivity in humans, remain controversial." (PMID 24072088, 2013). "This suggests that resistin may play an important role in obesity and obesity-associated disease by triggering the release of other proinflammatory cytokines." (PMID 22567283, 2012).
Obesity (continued). "The proinflammatory profile of resistin, together with its association with obesity, suggests that this adipokine might be another potential mediator that links OA with inflammation and obesity." (PMID 22910888, 2012). "The proinflammatory profile of resistin, together with its association with obesity suggest that this adipokine might be another potential mediator that links OA with inflammation and obesity." (PMID 22046513, 2011). "Our bioinformatic analysis reports resistin gene as ominous link with obesity associated diabetes." (PMID 23675069, 2008). "Moreover, in patients with type 2 diabetes, serum resistin levels are correlated with levels of soluble tumor necrosis factor α receptor, an inflammatory marker linked to obesity, insulin resistance, and atherosclerosis." (PMID 15578112, 2004). "Moreover, obesity is associated with activation of innate immunity, including the inflammatory mediators that induce resistin." (PMID 15578112, 2004). "However, resistin remained a strong predictor in both sexes, suggesting that its association with obesity may be a more universal mechanism that is less affected by sex hormones." (PMID 41315571, 2025). "Finally, resistin is another gene that may mediate this link, as it is associated with obesity, insulin resistance, and breast cancer risk, and is expressed higher in the tumors of Black women than in White women." (PMID 38816709, 2024). "In this way, resistin could contribute to the development of atherosclerosis caused by obesity." (PMID 39125315, 2024). "Thus, we can expect that new blockers of CB1R or resistin may be a promising solution to modulate adipose tissue inflammation associated with obesity and metabolic diseases." (PMID 39050819, 2024). "It has been reported that leptin, resistin, and adiponectin, which are involved in mediating obesity, have been linked to increased oxidative stress and inflammation, which may cause a global health risk leading to hyperglycemia, cancer, diabetes, and other diseases affecting vital organs." (PMID 36500974, 2022). "Obesity is also considered one of the OA risk factors due to it increasing the mechanical stress on the knee joint and adipocytes under obesity and release adipokines, such as leptin and resistin with elevated levels of proinflammatory cytokines and matrix metalloproteinases." (PMID 35509713, 2022). "Metabolic/obesity-associated dysregulation in HS was detected through type I diabetes mellitus signaling, lipid and atherosclerosis, C-type leptin receptor signaling, estrogen-dependent nuclear events and extranuclear signaling, adipogenesis and resistin signaling." (PMID 35056940, 2021). "Finally, resistin has been associated with obesity, insulin resistance, and T2DM." (PMID 35096868, 2021). "Therefore, we hypothesized that changes in gut microbiota may affect the expression of adiponectin and resistin in obesity, and the underlying mechanisms may be involved in gene epigenetic modification." (PMID 32586265, 2020). "Therefore, decreasing leptin and resistin concentrations may be considered a therapeutic target to reduce the inflammatory state associated with obesity." (PMID 33007981, 2020). "Thus, adipose tissue-linked systemic inflammation in KO vs. WT mice might be indicated by higher levels of leptin and resistin, adipokines contributing to the systemic low-grade inflammatory milieu in obesity and associated metabolic disorders." (PMID 31349725, 2019). "The association with resistin, however, remained strong and significant after adjusting for BMI, suggesting that resistin may be an important biomarker of cancer mortality among Blacks above and beyond the influence of obesity and/or insulin resistance." (PMID 29662629, 2018).